EGFR (epidermal growth factor receptor)
Diseases named in the same sentence as EGFR in open-access papers (continued):
Sharing a sentence is not in itself a finding about the gene and the disease.
lung cancer (continued). "EGFR is highly expressed in lung cancer, breast cancer, human glioblastoma, gastric carcinoma, rectal cancer, and head and neck cancer compared to healthy tissues." (PMID 35223483, 2022). "To extend these in vitro results, we conducted xenograft studies using cell line models of EGFR-mutant lung cancer (HCC827 and PC9)." (PMID 35326664, 2022). "EGFR and Caspase 3V266F are the protein targets related tothe lung cancer and cervical cancer, respectively." (PMID 37654842, 2022). "In vitro, this formulation was efficiently taken up by lung cancer cells, with a consequent reduction in EGFR activation, and 5–10 times higher cancer cell cytotoxicity compared with the free drugs." (PMID 35626078, 2022). "Reportedly, DDX59 is highly expressed in lung adenocarcinoma tissues and contributes to the growth of EGFR− lung cancer cells." (PMID 35113786, 2022). "It suggests that targeting the NF-kB/miR-155/FOXO3a pathway has potential therapeutic value in lung cancer with the acquisition of resistance to EGFR-TKIs." (PMID 35584089, 2022). "All these findings are suggesting a combination of AhR inhibitor and EGFR TKIs as a novel therapeutic strategy to treat lung cancers." (PMID 35831824, 2022). "Studies on the effects of different muscarinic agonists on lung cancer indicate that the activation of the EGFR/PI3K/AKT pathway is due to M3 activation." (PMID 35565451, 2022). "In the present study, we compared the in vitro efficacy of EGFR inhibitors (afatinib and allitinib) and conducted a comprehensive analysis of the molecular mechanisms triggered by KRAS mutations in a panel of lung cancer cell lines." (PMID 35887120, 2022). "Although TKIs targeting EGFR have shown tremendous clinical benefits in lung cancer, this is only true in patients with target activation." (PMID 36081848, 2022). "To confirm the functional role of putative fusions in the context of drug resistance, we developed an in vitro system using EGFR del19 mutant lung cancer cell line PC-9 and CRISPR-Cas9 technology." (PMID 36153311, 2022). "Survival differed significantly in different stages and with different EGFR mutation statuses between the LCF and single lung cancer groups." (PMID 36233811, 2022). "Several driver genes have been identified in lung cancer, such as epidermal growth factor receptor (EGFR), anaplastic lymphoma kinase (ALK), and Kirsten rat sarcoma virus oncogene homolog (KRAS)." (PMID 35582531, 2022). "Existing evidence indicates that HDAC inhibitors repress lung cancer cells proliferation and overcome resistance to EGFR inhibitors." (PMID 35188360, 2022). "In conclusion, this is the first study of the gastrointestinal microbiota in patients with EGFR-WT and EGFR-mutant lung cancer." (PMID 36076157, 2022). "Compared with testing other lung cancer driver genes, such as EGFR and KRAS, the application of NGS in the diagnosis of MET alterations is not very efficient, especially for METex14 skipping mutation." (PMID 36212500, 2022). "The average protein abundances among representative lung cancer proteins, EGFR, CDK1, and MAP2K1, revealed good linearity between the measured protein abundance and increasing cell numbers." (PMID 35013269, 2022). "Aurora B phosphorylates BUB1 to facilitate spindle assembly checkpoint signaling, and target Aurora B kinase can prevent and overcome resistance to EGFR inhibitors in lung cancer." (PMID 36176446, 2022). "Examples of using CRISPR/Cas9 include models of EGFR exon 20 mutations to study the efficacy of the EGFR tyrosine kinase inhibitor (TKI) osimertinib, or ablation of Aurora-B that re-sensitizes resistant lung cancer cell lines to cisplatin." (PMID 35205694, 2022). "We show that erlotinib, an FDA-approved EGFR inhibitor for the treatment of lung cancer inhibits PTK6, AKT, and ERK1/2 in cells that overexpress active PTK6." (PMID 36228719, 2022).
lung cancer (continued). "Results showed that wtEGFR forms nanoclusters at the plasma membrane of both normal and lung cancer cells, but the number and size of these clusters is significant larger in EGFR-overexpressing cancer cells (~300 nm v ~200 nm dia)." (PMID 35158954, 2022). "Large-scale cohort analysis revealed that expression of HSP27 and mutant EGFR were closely related to the prognosis of lung cancer patients." (PMID 35931945, 2022). "In this study collecting data from the TCGA database, we found that lung cancer tissues from EGFR TKI-resistant NSCLC patients had a hyperactive Hedgehog pathway than those from TKI-sensitive counterparts." (PMID 35154464, 2022). "The recent publication demonstrates that hypoxia-induced ZEB1 is involved in EGFR inhibitor resistance in lung cancer." (PMID 35798695, 2022). "EGFR regulates stemness in several cancer types and treatment of EGFR inhibitors regulates the appearance of stemness in lung cancer cells." (PMID 35745583, 2022). "MiR-19a is a critical oncogenic family member of the miR-17-92 cluster since it promotes proliferative EGFR signaling in lung cancer." (PMID 35885514, 2022). "Epidermal growth factor receptor (EGFR), a receptor tyrosine kinase, has been demonstrated to be highly expressed in many epithelial tumors, including lung cancer." (PMID 35497180, 2022). "The successful use of the first-generation EGFR kinase inhibitors gefitinib and erlotinib to treat EGFR mutant positive NSCLC in the early 2000s were among the first of these developments to pave the way for targeted therapies in lung cancer." (PMID 34913823, 2022). "In this review, we provide an overview of metabolism in cancer and then explore in more detail the role of lipid metabolic reprogramming in lung cancer development and progression and in resistance to therapies, emphasizing its connection with EGFR signaling." (PMID 35159223, 2022). "CAFs remodel actin cytoskeleton-induced EMT process in an Smo-dependent manner, enhancing the insensitivity of lung cancer cells to EGFR-TKIs." (PMID 35433472, 2022). "For patients with advanced lung cancer, survival in patients with mutant epidermal growth factor receptor (EGFR) was longer than that in patients with undetected EGFR." (PMID 36233811, 2022). "Although EGFR-TKIs have an excellent initial clinical therapeutic effect, the intrinsic resistance and acquired resistance to EGFR-TKIs pose a major barrier to the widespread use of EGFR-TKIs in clinical lung cancer treatment." (PMID 35163707, 2022). "For example, the glycosylation of epidermal growth factor receptor (EGFR) inhibits the abnormal phosphorylation of EGFR in TKI-resistant lung cancer cell line; the N-glycosylation at N359 ameliorated the hyperphosphorylated and aggregated of tau." (PMID 36277408, 2022). "The EGF/EGFR signaling pathway has been reported to regulate DSB repair in lung cancer cells following X-irradiation by promoting both the NHEJ and HR pathways." (PMID 35502895, 2022). "Flow cytometry analysis has shown that exosomes from the human lung cancer cell line A549 (A-Exo) had higher EGFR expression than exosomes from the human embryonic lung fibroblast HELF (H-Exo)." (PMID 35158999, 2022). "The resistance to epidermal growth factor receptor (EGFR)- tyrosine kinase inhibitors (TKIs) therapy is currently the major clinical challenge in the treatment of lung cancer." (PMID 35027025, 2022). "The ability to use EGFR inhibitors in PTPRH mutant lung cancers is a new area for investigation and is the primary impact of this research." (PMID 36054194, 2022). "Epidermal growth factor receptor (EGFR)‐targeted therapy is a common and essential means for the clinical treatment of lung cancer." (PMID 35838331, 2022).
lung cancer (continued). "Increased expression of Axl and its ligand Gas6 was found in EGFR-mutant lung cancers obtained from individuals with acquired resistance to erlotinib." (PMID 36059952, 2022). "Moreover, GEO data regarding gene-edited mouse models revealed that the expression of hub genes increased with the progression of NSCLC, and cohort study in lung cancer showed that the hub genes may be involved in EGFR- or KRAS-mutation driven NSCLC progression." (PMID 36176446, 2022). "In this regard, alterations in exon 19 of the EGFR gene in lung cancer are a promising biomarker, which reflects the maximum scores in the database." (PMID 37181287, 2022). "A few clinical studies have examined EGFR-TKI therapy in patients with EGFR-positive lung cancer and poor PS." (PMID 34643820, 2022). "FN also improves drug sensitivity to gefitinib, the epidermal growth factor receptor inhibitor acting on lung cancer cells." (PMID 36139871, 2022). "In a study of 299 patients with lung cancer, patients treated with gefitinib (an EGFR TKI) had lower TC levels after 30 days of treatment." (PMID 36017084, 2022). "This review scientifically summarizes the present knowledge regarding the biogenesis and biological functions of ncRNAs, including the formation of dysregulated ncRNAs in EGFR TKI-resistant lung cancer." (PMID 36139582, 2022). "Both EGFR and MET pathways have been implicated in driving tumor growth in lung cancer and in particular, MET pathway activation via upregulation of MET expression has frequently been described a mechanism of EGFR kinase inhibitor resistance." (PMID 34913823, 2022). "Cucurbitacin IIb mediated inhibition of EGFR/mitogen-activated protein kinase (MAPK) pathway leads to G2/M phase cell cycle arrest in lung cancer cells." (PMID 35273218, 2022). "Molecularly targeted cancer therapy has improved outcomes for patients with cancer with targetable oncoproteins, such as mutant EGFR in lung cancer." (PMID 35579943, 2022). "Despite the vast majority of EGFR mutant lung cancer patients treated with EGFR tyrosine kinase inhibitors (TKIs) derive clinical benefit, acquired drug resistance is inevitable." (PMID 35197546, 2022). "For example, epidermal growth factor receptor (EGFR) mutations and ALK rearrangements are usually indicative of a lung cancer origin (most CUP cases), while BRAF and NRAS mutations are associated with melanoma." (PMID 35225863, 2022). "At present, studies have shown that EGFR can promote cell division and proliferation, and up-regulated expression in many malignant tumors, including lung cancer." (PMID 36384712, 2022). "Here, the authors describe the structural basis and molecular mechanism by which allosteric and clinically approved, ATP-competitive inhibitors of EGFR synergize to overcome resistance in lung cancer." (PMID 35534503, 2022). "HCC827 and H1975 human lung cancer cells are model cell lines for epidermal growth factor receptor (EGFR)-mutant nonsmall cell lung cancer." (PMID 36137002, 2022). "Latest results have shown that around 83% of the lung cancer patients included in the cohort study (n = 2.204) were tested for EGFR, ALK, ROS-1, PD-L1 and / or BRAF." (PMID 35765059, 2022). "Through evaluation including RNA-seq of potential drug resistance-imparting fusion oncogenes in 504 patients with EGFR mutant lung cancer, we identify only a minority of them as functional, potentially capable of imparting EGFR inhibitor resistance." (PMID 36153311, 2022). "DHA decreased the cell viability in H1299, and KRAS-mutant A549 and LLC1 lung cancer cells in a dose-dependent manner, via the EGFR and downstream proteins’ inhibition." (PMID 36547898, 2022).
lung cancer (continued). "Several EGFR-targeting therapeutic agents are currently used for patients with EGFR-positive lung cancer, including receptor tyrosine kinase inhibitors such as afatinib, dacomitinib, erlotinib, gefitinib, and osimertinib." (PMID 36361596, 2022). "Uncontrolled activity of the EGFR can act as an active oncogenic driver and target for precision medicine intervention in lung cancer cells." (PMID 35677717, 2022). "For example, trastuzumab is used for HER2-amplified breast cancer BrM, tragisso (Osimertinib) for EGFR-mutant lung cancer BrM, and xalkori (Crizotinib), alecensa (Alectinib), alunbrig (Brigatinib), and zykadia (Ceritinib) against ALK-rearranged BrM." (PMID 35225863, 2022). "Among the studied chemokines and cytokines, IL-6, which was reported to induce EGFR-TKI resistance in EGFR-mutant lung cancer through paracrine STAT3 activation, was highly expressed in EGFR wild-type A549 cells in our study." (PMID 36612121, 2022). "It captured pathways related to resistance such as “mechanisms of resistance to EGFR inhibitors in lung cancer” and “Anti-apoptotic action of ErbB2 in breast cancer”." (PMID 35351890, 2022). "Lung cancer with EGFR exon 19 deletion is known to have the greatest prevalence, which is present in 1.57% of AACR GENIE cases." (PMID 35463301, 2022). "Non-small cell lung cancer, EGFR, targeted therapy, lung cancer, EGFR-TKI, erlotinib, chemotherapy, cancer, sunitinib, and resistance all appear in the top 10 list of degree centralization and closeness centralization." (PMID 35072634, 2022). "In order to model PFS in EGFR-mutant LA, we leveraged our experience with an in vivo luciferase-based orthotopic lung cancer model." (PMID 35579943, 2022). "In another study, AuNPs were conjugated with a PS C11Pc and an EGFR peptide AEYLR to target EGFR markers expressed in lung cancer." (PMID 36230480, 2022). "Here we present four patients with EGFR mutant lung cancer whose drug resistant cancers contained putative fusion oncogenes." (PMID 36153311, 2022). "This mutation causes resistance to epidermal growth factor tyrosine kinase inhibitors (EGFR TKIs) which are commonly used in the treatment of advanced lung cancer." (PMID 36497303, 2022). "Curcumin has been shown to down-regulate Epidermal Growth Factor Receptor (EGFR) thereby inhibiting cell proliferation of multiple cancer cells, including lung cancer." (PMID 35685638, 2022). "We report here a case of histologically undiagnosed lung cancer managed with a liquid biopsy and subsequently with anti-EGFR treatment." (PMID 36579578, 2022). "Phosphorylated EGFR can trigger downstream signaling to promote proliferation, metastasis, and angiogenesis of lung cancer cells." (PMID 36232998, 2022). "In this review, we explored the role of lipid metabolic rewiring in lung cancer development and progression and in resistance to therapies, focusing in particular on its connection with EGFR signaling." (PMID 35159223, 2022). "Given the significance of targeted therapy in lung cancer, the mechanism of EGFR-TKI resistance was extensively characterized and mainly focused on EMT pathway." (PMID 36304306, 2022). "Epidermal growth factor receptor (EGFR) overexpression has been observed in many cancers, including breast cancer, lung cancer, colorectal and esophageal cancer." (PMID 35630793, 2022). "MGL S3 downregulates EGFR mRNA level in breast and lung cancer cell lines, and the EGFR inhibitor gefitinib enhances the sensitivity of H1299 cells to MGL S3." (PMID 36361596, 2022). "Fusion genes have been proposed as a potential mechanism of resistance to EGFR tyrosine kinase inhibitors (TKIs) in lung cancer." (PMID 36153311, 2022).
lung cancer (continued). "The MET receptor tyrosine kinase (RTK) and its ligand hepatocyte growth factor (HGF) play an important role in cancer development as well as in innate and acquired resistance to lung cancer treatment, including EGFR inhibition." (PMID 36230855, 2022). "Among patients with lung cancer, NM occurs most frequently with epidermal growth factor receptor (EGFR) positive non-small cell lung cancer (NSCLC)." (PMID 36612116, 2022). "The SPR platform detected higher levels of EVs EGFR and PD-L1 in the serum of lung cancer patients compared to healthy individuals isolated exosomes." (PMID 35880114, 2022). "EGFR-TKIs represent the mainstream treatment for EGFR-mutant lung cancer, but resistance inevitably develops." (PMID 36612121, 2022). "In this context, our efforts aimed to investigate the role of Avns, an important class of molecules derived from oat, as anti-cancer compounds in EGFR-dependent lung cancer progression." (PMID 35955669, 2022). "GPR155 mutation was frequently detected in acquired resistance time point in lung cancer patients only in the EGFR-TKI treated group." (PMID 35402275, 2022). "Studies have shown that in lung cancer, the saliac acid sites (N32, N151, and N389) of EGFR are usually close to the surface-binding sites of EGF." (PMID 36092699, 2022). "Other studies have also demonstrated an inverse correlation between TMB and prognosis with targeted therapies in EGFR‐mut lung cancer patients exhibiting poor responses to immunotherapy." (PMID 35521981, 2022). "In conclusion, our study shows that 2D5 peptide is a novel anticancer peptide that inhibits STAP-2–mediated activation of EGFR signaling and suppresses prostate and lung cancer progression." (PMID 36410436, 2022). "We also underscore the clinical application of ncRNAs as prognostic, predictive and therapeutic biomarkers for EGFR TKI-resistant lung cancer." (PMID 36139582, 2022). "Its receptor EGFR has been extensively explored as a therapeutic target against multiple types of cancers, such as lung cancer and glioblastoma." (PMID 35931120, 2022). "CXCL10 is secreted primarily by monocytes, but EGFR-mutant lung cancer cells have also been shown to produce CXCL10 in response to IFN-γ." (PMID 36612121, 2022). "In this study it was shown by significantly impairing the effectiveness of treatment with EGFR TKIs, canagliflozin inhibits L858R/T790M EGFR kinase anticancer activity in lung cancer cells that are resistant to EGFR TKIs." (PMID 36497303, 2022). "The authors have demonstrated that the silencing of either CARD10 or MALT1 in EGFR-overexpressing lung cancer cells correlates with reduced NF-κB activity, cancer cell proliferation, migration, survival, and tumor burden in vivo." (PMID 35203553, 2022). "EGFR overexpression is frequently found in lung cancer tissues and plays a key role in promoting lung cancer propagation." (PMID 36358752, 2022). "Although osimertinib is frequently used for its potential beneficial outcomes in first- and late-line settings, almost all patients with EGFR-mutant lung cancer ultimately acquired resistance to osimertinib after approximately 20 months." (PMID 36082280, 2022). "The increasing use of osimertinib in the first line therapy of EGFR mutant lung cancer is leading a change to testing strategies." (PMID 35820813, 2022). "A large number of studies have found that high expression or abnormal activation of EGFR is closely related to the occurrence, development, recurrence, metastasis, and drug resistance of lung cancer." (PMID 35706930, 2022). "Our CRISPR models using EGFR mutant lung cancer cell lines, enabled precise evaluation of the biology and drug resistance as a result of a concurrent fusion oncogene which would not have been possible using conventional simple Ba/F3 models." (PMID 36153311, 2022).